MEN1 (menin 1)
Diseases named in the same sentence as MEN1 in open-access papers (continued):
Sharing a sentence is not in itself a finding about the gene and the disease.
parathyroid adenomas (continued). "Approximately 25–40% of all sporadic parathyroid adenomas harbor LOH of the MEN1 gene locus at 11q13, and half of these cases also exhibit an inactivating MEN1 mutation of the remaining allele." (PMID 33269427, 2021). "Considering that Chr.11-LOH occurs in about 40% of parathyroid adenomas and MEN1 expression is variably conserved in parathyroid tumors, we chose to silence MEN1 gene expression in order to evaluate the effect of its complete loss." (PMID 34199594, 2021). "MEN1 is a hereditary syndrome clinically defined by the presence of two of the following endocrine tumors in the same patient: parathyroid adenomas, entero-pancreatic endocrine tumors and pituitary tumors." (PMID 30459713, 2018). "Certain germinal mutations of MEN1, which encodes MENIN, cause multiple endocrine neoplasia type 147, which is an autosomal dominant syndrome characterized by concurrent parathyroid adenomas, gastroenteropancreatic tumors, and several other tumor types." (PMID 30120246, 2018). "The clinical diagnosis of this syndrome is done by diagnosing 2 of the 3 major MEN1 related endocrine tumors in the patient, which are parathyroid adenomas, entero-pancreatic endocrine tumors, and pituitary tumors." (PMID 30459713, 2018). "miR-24-1 expression profiles have been conducted in some MEN1 parathyroid adenomas fromMEN1 mutant carriers, their sporadic non-MEN1 counterparts, and in normal parathyroid tissue." (PMID 28184288, 2017). "There was significantly increased genome-wide DNA methylation in MEN1-parathyroid tumors compared to normal human parathyroid tissues, sporadic parathyroid adenomas, and parathyroid cancers." (PMID 26871472, 2016). "While 466,950 loci were significantly hypermethylated in MEN1-parathyroid tumors, only 48,162 and 27,169 loci were significantly hypermethylation in parathyroid adenomas and parathyroid carcinomas respectively, when compared to normal parathyroids." (PMID 26871472, 2016). "In the present study, we analyzed the expression profile of miR-24-1 in parathyroid adenomas from MEN1 patients, with different MEN1 mutations, in which the main difference was the MEN1 LOH or the maintenance of the wild type MEN1 allele." (PMID 22761894, 2012). "Northern blot analysis was performed to analyze the expression level of miR-24-1 in MEN1 parathyroid adenomas, in sporadic parathyroid adenomas and in one normal parathyroid tissue." (PMID 22761894, 2012). "MEN1 parathyroid adenomas consist of multiple morphologically distinct nodules and micronodules." (PMID 38244045, 2024). "In addition, miR-4258 was reported to be down-regulated in MEN1 LOH+ parathyroid adenomas, and it is predicted to target and inhibit the CCDN1 gene encoding the cyclin D1, which is a positive regulator of the cell cycle and cell growth." (PMID 39519139, 2024). "MEN1, a tumor suppressor that are confirmed frequently mutated in sporadic parathyroid adenoma, was detected with no mutation in these THPT samples." (PMID 37854190, 2023). "Recent studies suggest that mutation in MEN1, POT1 and RAP1B can also cause parathyroid adenomas." (PMID 34803267, 2020). "In addition to MEN1 and CCND1, other genes that participate in the development of parathyroid adenoma include those encoding cyclin-dependent kinase inhibitors, along with CTNNB1, EZH2, ZFX, GCM2, and CASR." (PMID 30832348, 2019). "Other sporadic parathyroid adenoma tissues were screened for MEN1 gene mutations by direct sequencing and no additional missense or truncating mutations were found." (PMID 26871472, 2016). "Interestingly, a single sporadic parathyroid adenoma clustered together with the MEN1-parathyroid tumor group and showed a global hypermethylation phenotype as well." (PMID 26871472, 2016).
parathyroid adenomas (continued). "Mature miR-24-1 was expressed only in MEN1 parathyroid adenoma tissues that conserved the wild-type allele (without MEN1-LOH), but not in the MEN1 parathyroid adenoma tissues that lost the MEN1 gene (with MEN1-LOH), as well as in sporadic parathyroid adenomas." (PMID 22761894, 2012). "If miR-24-1 was a negative tissue-specific regulator of the menin oncosuppressor protein, then miR-24-1 should be over-expressed in MEN1 parathyroid adenomatous tissues versus sporadic non-MEN1 forms of parathyroid adenomas as well as in healthy parathyroid tissue." (PMID 22761894, 2012). "In order to check this hypothesis, we analyzed both the expression of MEN1 mRNA and menin protein in MEN1 and in sporadic parathyroid adenoma tissues." (PMID 22761894, 2012). "Finally, the clinical management of MEN1 parathyroid adenomas is an ongoing debate." (PMID 38244045, 2024). "Thus, the expression of this miRNA only in MEN1 parathyroid adenomas could account for selective parathyroid tumorigenesis, mimicking and substituting the second somatic ‘‘hit’’ of the TSG inactivation, even before the occurrence of LOH." (PMID 39519139, 2024). "In particular, they evaluated the expression levels of MEN1 mRNA and menin protein, and miR-24-1, in eight MEN1 parathyroid adenoma tissues (four without and four with loss of heterozigosity (LOH) of MEN1 gene), three non-MEN1 PA tissues, and one normal parathyroid gland tissue." (PMID 34638805, 2021). "This case should raise awareness among physicians of the possibility of MEN1 in patients with urinary tract stones, and that timely assessment of blood calcium and PTH levels is essential, allowing early detection of parathyroid adenoma and surgical treatment." (PMID 40421248, 2025). "CaSR, MEN1, CCND1/PRAD, CDKI, angiogenic factors like VEGF, FGF, TGFβ, and IGF1, and apoptotic factors are important genes in parathyroid adenomas pathogenesis that have been established by several studies." (PMID 37223014, 2023). "In this syndrome, age has no bar, and it occurs in both men and women.The tumour-suppressor gene MEN1 and proto-oncogene CCND1 are well known key driver genes for sporadic parathyroid adenoma." (PMID 34803267, 2020). "To date, MEN1 and CCND1 (respectively, a tumor suppressor and a proto-oncogene) are the most solidly established molecular drivers of sporadic parathyroid adenoma." (PMID 30832348, 2019). "While parathyroid hyperplasia shows diffuse, nodular, or mixed growth patterns, typical morphological stigmata for MEN1 parathyroid adenomas have not been reported." (PMID 38244045, 2024). "miR-1301 resulted upregulated in MEN1 LOH parathyroid adenomas, both with respect to the MEN1 non-LOH parathyroid adenomas and the non-MEN1 controls." (PMID 34298972, 2021). "presented the case of a 47-year-old male patient with MEN1 who was affected by parathyroid adenomas, non-functioning pancreatic tumors and a metastatic prolactinoma presenting as a cervical spinal cord lesion." (PMID 33312161, 2020). "Occupancy of miR-24-1 promoter region was observed only in MEN1 parathyroid adenoma tissues without LOH (that conserved the wild-type copy of MEN1 allele), when compared to MEN1 parathyroid adenoma tissues with LOH and to control IgG." (PMID 22761894, 2012). "The miR-1301-3p was selected for the present study since in a previous study by our Research Group, it was found to be differentially regulated in MEN1 parathyroid adenomas with LOH at 11q13 locus compared to the non-LOH counterpart and healthy parathyroid tissue." (PMID 40507887, 2025). "Overall, their findings suggest that the expression of this miRNA only in MEN1 parathyroid adenoma tissues without LOH could be responsible for parathyroid tumorigenesis previous to the MEN1 LOH occurrence." (PMID 34638805, 2021). "Unlike sporadic parathyroid adenomas, MEN1-related tumors are often devoid of a rim of normal parathyroid tissue, and they may be composed of chief cells arranged in compact, sheet-like formations." (PMID 33269427, 2021).
parathyroid adenomas (continued). "Conversely, a single parathyroid adenoma, whose excision resulted in the cure of PHPT, was found in 9/14 (64%) and 9/15 (60%) MEN1 mutation-negative probands and patients of the whole cohort submitted to PTx, respectively [mean follow-up 7yr (SD 4)] (P<0.0001 in both groups)." (PMID 29036195, 2017). "DNA methylation and chromatin modifications, for example, may contribute to the pathogenesis of HPT, although the MEN1 gene itself does not appear to be subject to methylation changes and parathyroid adenomas do not appear to be affected by global methylation patterns." (PMID 33716975, 2021). "miR-1301-3p was selected since it had been demonstrated to be upregulated in LOH MEN1 parathyroid adenomas, both with respect to non-LOH MEN1 parathyroid adenomas and control tissue." (PMID 40507887, 2025). "miR-4258 resulted remarkably downregulated in MEN1 parathyroid adenomas with MEN1 LOH, with respect to those without MEN1 LOH." (PMID 34298972, 2021). "Western blot in lysates from both MEN1 parathyroid adenomas with MEN1-LOH and without MEN1-LOH showed almost undetectable levels of menin expression with respect to the sporadic forms and the normal parathyroid tissue." (PMID 22761894, 2012).
parathyroid tumors (64 papers, 2010 to 2025). "The importance of menin in parathyroid proliferation is also highlighted by the presence of MEN1 somatic variants, such as intragenic deletions, in sporadic parathyroid tumours." (PMID 40364143, 2025). "[18F]FCH PET/CT offers a favorable benefit-to-risk ratio in detecting parathyroid tumors in MEN1 cases." (PMID 39795539, 2024). "With regard to Wnt/β-catenin signaling, multiple members of the Sox gene family are hypermethylated and downregulated in murine menin knockout tumors and in MEN1-deficient parathyroid tumors compared to benign parathyroid tissue." (PMID 39336822, 2024). "A profile analysis of lncRNA expression in parathyroid tumors, including some with MEN1 mutations, showed that the tumors exhibiting MEN1 gene mutations had an increased expression of six lncRNAs, including BC200, HAR1B, HOXA3as, NEAT1, SNHG6, and ZFAS1." (PMID 39519139, 2024). "Parathyroid tumorigenesis in MEN1 results from the combination of a germline MEN1 mutation together with a somatic mutation occurring in a parathyroid tumor precursor cell." (PMID 39519139, 2024). "Parathyroid neoplasms can also be associated with multiple endocrine neoplasia (MEN) syndromes MEN1, MEN2A, and MEN4, caused by mutations in the genes MEN-1, RET, and CDKN1B, respectively." (PMID 36900197, 2023). "A microarray-based analysis was initially performed to identify differentially expressed miRNAs between sporadic and MEN1-associated parathyroid tumors compared to healthy parathyroid tissues." (PMID 34638805, 2021). "Apart from being involved in the mentioned familial syndrome, somatic mutations of MEN1 gene are also implicated in the development of sporadic parathyroid tumors." (PMID 22567348, 2011). "Sporadic parathyroid tumors harboring MEN1 gene somatic mutations frequently evidence LOH on chromosome region 11q13." (PMID 22567348, 2011). "Patients develop MEN1-associated tumors, including parathyroid tumors (approximately 80% of patients) and anterior pituitary tumors that are typically smaller and less aggressive than MEN1, in association with tumors of the kidneys, adrenals and reproductive organs." (PMID 39336996, 2024). "Results from this study suggested that, in MEN1-associated parathyroid tumors, after the first inherited germinal “hit”, the somatic onset and progression of neoplasia could be under the control of a negative feedback loop between menin protein and miR-24-1." (PMID 34298972, 2021). "In conclusion, we identified that miR-199b-5p is differentially expressed between sporadic and MEN1 parathyroid tumors and could be a potential diagnostic marker for distinguishing these tumors in different genetic backgrounds." (PMID 30104706, 2018). "Interestingly, frequency of MEN1 mutation was also only 25% in 32 pedigrees of familial occurrence of tumors of parathyroids and pituitary gland." (PMID 30254610, 2018). "However, the occurrence of MEN1 mutations tumors in patients developing parathyroid tumors below the age of 40 years has been reported to be higher at 5–13%." (PMID 23933118, 2014). "About 30% of sporadic parathyroid tumors show MEN1 gene mutations." (PMID 22567348, 2011). "However, APC promoter 1A methylation displayed a weak but significant correlation to the tumour suppressor MEN1 genotype, and all parathyroid tumours with MEN1 mutations in our panel displayed APC hypermethylation ranging from 11.6–65.9%." (PMID 20208994, 2010). "The molecular pathogenesis of parathyroid tumors has already been partly elucidated; Heppner and Carling have reported that inactivating somatic mutations of tumor suppressor genes multiple endocrine neoplasia type 1 (MEN1), RET, and HRPT2/CDC73 have been identified in parathyroid tumors." (PMID 35879975, 2022). "Moreover, we hypothesized that the known tumor suppressor menin, encoded by the MEN1 gene, whose expression is lost in multiple endocrine neoplasia (MEN1)-related parathyroid tumors, may be involved in the modulation of the core stem genes." (PMID 34199594, 2021).
parathyroid tumors (continued). "However, the sole occurrence of parathyroid tumors in these families that harbor MEN1 mutations that are similar to those found in families with MEN1 is remarkable, and the mechanisms that determine the altered phenotypic expressions of these mutations remain to be elucidated." (PMID 23933118, 2014). "MEN1 is characterized by co-occurrence of tumors of the parathyroid gland, pancreas, and pituitary gland." (PMID 40421248, 2025). "Men1 heterozygotic mice with parathyroid neoplasms were hypercalcaemic and hypophosphataemic, with inappropriately normal serum parathyroid hormone concentrations." (PMID 39409111, 2024). "Radionuclide imaging, especially PET/CT using radiopharmaceuticals like [18F]FCH, shows promising results in localizing parathyroid tumors, particularly in patients with MEN1." (PMID 39795539, 2024). "Tumors of the parathyroid, the anterior pituitary gland, and the entero-pancreatic system are most frequent in MEN1." (PMID 38244045, 2024). "MEN1 is characterized by tumors in the parathyroids, pituitary, and pancreas, although other tumors can be found, including adrenal cortical adenomas and bronchopulmonary and thymic tumors." (PMID 38038882, 2024). "The malignant transformation of parathyroid tumors is uncommon, even if rare cases of parathyroid carcinoma have been reported in MEN1 patients, with only 21 cases reported in recent literature." (PMID 39336996, 2024). "Before the identification of the MEN1 gene in the late 1990s, parathyroid tumors in MEN1 were considered as the result of a polyclonal expansion." (PMID 39519139, 2024). "Mutations on CDC73, MEN1, HIC1, EZH2, and β-catenin genes, demonstrated to be involved in parathyroid tumors, seem to implicate epigenetic modifications in their mechanism of tumorigenesis." (PMID 35628190, 2022). "In contrast, the patients with recurrent PHPT were more likely to have genetic alterations, such as MEN1 or parathyroid cancer, so that they had the recurred disease even after the complete resection of the initial parathyroid tumor." (PMID 35586626, 2022). "Tumor suppressor gene mutations such as MEN1 and CDC73 were demonstrated to be involved in tumor development in both familiar and sporadic types; however, the epigenetic features of the parathyroid tumors are still a little-explored subject." (PMID 35628190, 2022). "Inherited syndromic forms of parathyroid tumors include MEN1, Multiple Endocrine Neoplasia type 2A (MEN2A), Multiple Endocrine Neoplasia type 4 (MEN4), and HPT-JT syndrome." (PMID 34681865, 2021). "This suggests that MEN1 alterations occur early during parathyroid tumor formation, which is a wider presentation of parathyroid disease." (PMID 33778063, 2021). "Chromosome 11 loss of heterozygosity (LOH) can be detected in at least 40% of parathyroid tumors and MEN1, which maps on chromosome 11, is an important oncosuppressor involved in parathyroid tumorigenesis." (PMID 34199594, 2021). "Parathyroid tumors occur in about 95% of MEN1 patients, being the first endocrinopathy in 90% of cases, manifesting as synchronous or asynchronous adenomas affecting all four glands during patient’s life." (PMID 34681865, 2021). "In MEN1, pancreatic and lung (and rarely thymic) NENs occur with parathyroid tumours and anterior pituitary adenomas." (PMID 32554825, 2020). "First, the sample size of MEN1-related parathyroid tumors is small due to the rarity of this condition." (PMID 30104706, 2018). "Parathyroid tumors, resulting in primary hyperparathyroidism are the most common feature of MEN1 and occur in approximately 95% of patients." (PMID 28670351, 2017). "Parathyroid tumors are the most common clinical manifestation, and the prevalence of hyperparathyroidism is >90% in patients with MEN1, whereas those of pancreatic and pituitary tumors are 40–70% and 30–60%, respectively." (PMID 28969599, 2017). "Parathyroid tumors are often the first and the most frequent tumors, and occur in approximately 95% of MEN1 patients." (PMID 28881068, 2017).